CREBBP (CREB binding lysine acetyltransferase )
Diseases named in the same sentence as CREBBP in open-access papers (continued):
Sharing a sentence is not in itself a finding about the gene and the disease.
Chordoid Meningioma (1 paper, 2024). A WHO grade II, usually recurring meningioma characterized by the predominance of tissues that are histologically similar to chordoma. "Interestingly, the transitional meningioma (M1) had a second hit of NF2 and the chordoid meningioma (M2) had a CREBBP mutation." (PMID 39066986, 2024). "CREBBP is a chromatin-remodeling gene that is more enriched in chordoid than non-chordoid meningiomas." (PMID 39066986, 2024).
chordoma (1 paper, 2013). Chordomas are rare malignant tumors arising from embryonic remnants of the notochord in axial skeleton. "Six genes (NOTCH2, NCOR2, CREBBP, JAG1, KAT2A and NCSTN) related to the Notch signaling pathway were upregulated in chordoma tissues." (PMID 23826111, 2013).
Cirrhosis (1 paper, 2012). A chronic disorder of the liver in which liver tissue becomes scarred and is partially replaced by regenerative nodules and fibrotic tissue resulting in loss of liver function. "In line with up-regulation of miR-571, CREBBP was down-regulated in liver tissue from cirrhosis patients compared with healthy controls." (PMID 22412969, 2012).
ductal carcinoma (1 paper, 2021). "e The patients with ductal carcinoma (n = 1863) were filtrated for genetic alterations analysis of CREBBP and KAT2A genes." (PMID 33827682, 2021).
embryonal carcinoma (1 paper, 2020). A non-seminomatous malignant germ cell tumor characterized by the presence of large germ cells with abundant cytoplasm resembling epithelial cells, geographic necrosis, high mitotic activity, and pseudoglandular and pseudopapillary structures formation. "Generation of an iPSC neuronal model is highly relevant to RSTS given that the only human model exploring the role of CREBBP mutations during neural differentiation is represented by embryonal carcinoma cells (NT2 cells) transfected with CREBBP deletion constructs." (PMID 32562237, 2020).
energy metabolism disorder (1 paper, 2022). "For the biological characteristic of CREBBP, it is a key regulator for maintaining cellular energy homeostasis, which might be correlated with energy metabolism disorder in Yang or Yin deficiency symptoms." (PMID 35341155, 2022).
Ewing sarcoma (1 paper, 2023). A small round cell tumor that lacks morphologic, immunohistochemical, and electron microscopic evidence of neuroectodermal differentiation. "Moreover, some studies have also indicated that PIK3R1, NOTCH1, and CREBBP are common in recurrent Ewing sarcoma." (PMID 36964542, 2023).
Fanconi Anaemia (1 paper, 2022). "In addition, the top two enriched KEGG pathways were: 1) the Fanconi Anaemia pathway (represented by ATR, BRIP1, ERCC4, FANCC and POLH) and the FoxO signalling pathway (represented by CREBBP, NLK, PRKAA2, PRKAB1, PTEN and STK11)." (PMID 35768547, 2022).
fibromyxoid tumor (1 paper, 2018). A soft tissue tumor of uncertain lineage characterized by the presence of neoplastic spindle-shaped to round cells in a fibromyxoid stroma. "Interestingly, 2 ossifying fibromyxoid tumors with a CREBBP-BCORL1 fusion have been reported." (PMID 30514397, 2018).
fibrosis (1 paper, 2020). the formation of excess fibrous connective tissue in an organ or tissue in a reparative or reactive process. "Collectively, these data indicate CREBBP/EP300 is a highly associated pathway in localized human fibrosis that controls key aspects of myofibroblast phenotype and function, including ACTA2 and COL1A1 gene expression and cell contractility." (PMID 32759223, 2020).
gliosarcoma (1 paper, 2021). A rare histological variant of glioblastoma (WHO grade IV) characterized by a biphasic tissue pattern with alternating areas displaying glial and mesenchymal differentiation (WHO).
head and neck cancer (1 paper, 2022). A primary or metastatic malignant neoplasm affecting the head and neck. "Mutation of CREBBP has been previously linked to worse prognosis in solid tumour types including head and neck cancer and CRC." (PMID 35879507, 2022).
heart failure (1 paper, 2021). Inability of the heart to pump blood at an adequate rate to meet tissue metabolic requirements. "For the differential genes associated LMNA alone with euchromatin, we obtained 5 candidate genes (EGR2, NMB, CREBBP, PRF1, and TENM4), of which EGR2 and NMB have been reported to involve in myocardial ischemia and heart failure, respectively." (PMID 33407844, 2021).
Hemophagocytosis (1 paper, 2014). Phagocytosis by macrophages of erythrocytes, leukocytes, platelets, and their precursors in bone marrow and other tissues. "The MYST3/CREBBP rearrangement results in a cytomorphologically unique AML characterized by monocytic or myelomonocytic morphology, extramedullary involvement, DIC, and hemophagocytosis." (PMID 25548695, 2014). "The MYST3/CREBBP fusion protein results in a unique AML characterized by monocytic or myelomonocytic morphology, extramedullary involvement, disseminated intravascular coagulation (DIC), and hemophagocytosis." (PMID 25548695, 2014).
influenza (1 paper, 2013). An acute viral infection of the respiratory tract, occurring in isolated cases, in epidemics, or in pandemics; it is caused by serologically different strains of viruses (influenzaviruses) designated A, B, and C, has a 3-day incubation period, and usually lasts for 3 to 10 days. "CREBBP, PRKCD are implicated in MAPK signaling which is crucial for viral protein production and export while PRKAG2 is implicated in post-entry processes and autophagy in influenza infection." (PMID 24116168, 2013).
lung injury (1 paper, 2021). "To confirm our finding that ZFP36 could prevent CREBBP-induced lung injury through mRNA degradation, we measured the effect of altering the expression of ZFP36 on the level of CREBBP mRNA in the intestinal I/R-induced lung injury mouse model." (PMID 34238924, 2021).
male reproductive diseases (1 paper, 2022). "Our study demonstrated the important role of circ-CREBBP in sperm motility, and the circ-CREBBP/miR-10384 and miR-143-3p/MCL1, CREB1 and CREBBP signaling pathways might be promising diagnostic biomarkers and therapeutic targets for male reproductive diseases." (PMID 36476986, 2022). "Our study suggests that circ-CREBBP may be a promising biomarker and therapeutic target for male reproductive diseases." (PMID 36476986, 2022). "Our results suggest that circ-CREBBP may be a promising biomarker and therapeutic target for male reproductive diseases." (PMID 36476986, 2022).
mitral atresia (1 paper, 2025). "Patients in Group 2, the mitral atresia group, carried variants in the genes including EP300, NOTCH1, and TTN (mitral atresia), CREBBP, EP300, and NOTCH1 (hypoplastic left ventricle)." (PMID 41153298, 2025).
Myelodysplasia (1 paper, 2014). Clonal hematopoietic stem cell disorders characterized by dysplasia (ineffective production) in one or more hematopoietic cell lineages, leading to anemia and cytopenia. "The MYST3/CREBBP related AML tends to develop within 2 years of adjuvant chemotherapy, without preceding myelodysplasia, and is associated with an aggressive presentation, DIC, and a poor survival." (PMID 25548695, 2014).
myeloproliferative neoplasm (1 paper, 2016). A clonal hematopoietic stem cell disorder, characterized by proliferation in the bone marrow of one or more of the myeloid (i.e., granulocytic, erythroid, megakaryocytic, and mast cell) lineages. "Taken together, the data indicate that the coding sequence of CREBBP is not a relevant target of somatic alteration in JMML, in agreement with the absence of CREBBP mutations from myeloproliferative neoplasms in adults." (PMID 27158276, 2016).
neuroepithelial tumor (1 paper, 2024). "We found a reported BCOR::CREBBP fusion in a neuroepithelial tumor with breakpoints in exon 4 of BCOR and exon 31 of CREBBP in the literature." (PMID 38637838, 2024).
non-Hodgkin lymphoma (1 paper, 2021). Distinct from Hodgkin lymphoma both morphologically and biologically, non-Hodgkin lymphoma (NHL) is characterized by the absence of Reed-Sternberg cells, can occur at any age, and usually presents as a localized or generalized lymphadenopathy associated with fever and weight loss. "CREBBP is one of the most frequently mutated genes in non-Hodgkin lymphoma (NHL) and usually plays a tumour-suppressing role through epigenetic regulation." (PMID 33911074, 2021).
oral cancer (1 paper, 2016). "Examinations on clinical samples exhibited that MMP-9, CREBBP, and EP300 were significantly increased in oral cancer tissues." (PMID 26980735, 2016).
ovarian mucinous carcinomas (1 paper, 2025). "We identified several genes known to be mutated in ovarian mucinous carcinomas, including ERBB2, ARID1A, and CREBBP." (PMID 40981433, 2025).
parathyroid disease (1 paper, 2025). "Among these, several genes such as APC, CEP152, CREBBP, FAM111A, FGFR1, KL and MMP14 have been previously suggested to be associated with parathyroid disease." (PMID 40434298, 2025).
penile squamous cell carcinomas (1 paper, 2022). "CREBBP and FGF3 mutations have also been described in penile squamous cell carcinomas." (PMID 36564761, 2022).
pilomatrixoma (1 paper, 2015). Pilomatrixoma is a rare and benign hair cell-derived tumor occurring mostly in young adults (usually under the age of 20) and characterized as a 3-30 mm solitary, painless, firm, mobile, deep dermal or subcutaneous tumor, most commonly found in the head, neck or upper extremities. "A less strict follow-up protocol may be only appropriate for RSTS patients with EP300 mutations, with focus on skin problems (pilomatrixomas and nevi) that are likely more frequent than in patients with CREBBP mutations." (PMID 25599811, 2015).
psoriatic arthritis (1 paper, 2023). Joint inflammation associated with psoriasis. "The CREBBP and P300-specific (type A HATs) inhibitor (CBP30) reduced the induced Th17 response in patients with psoriatic arthritis." (PMID 37833997, 2023).
rectal cancer (1 paper, 2019). A primary or metastatic malignant neoplasm that affects the rectum. "In addition to SMAD7 (P = 0.0005) and SMAD3 (P = 0.0003), several other genes or genetic regions (CYP2R1, CHAF1A, CREBBP, IL10, SNPs identified in genome-wide association studies (GWAS) to be associated with IGF levels, IGFBP2/IGFBP5, IGFBP3, and C-MYC region) were associated with rectal cancer." (PMID 31434255, 2019).
Seizure (1 paper, 2021). A seizure is an intermittent abnormality of nervous system physiology characterized by a transient occurrence of signs and/or symptoms due to abnormal excessive or synchronous neuronal activity in the brain. "Seizures were reported to be more often frequent in RSTS patients with CREBBP mutations." (PMID 34795756, 2021).
small-bowel cancer (1 paper, 2021).
T-cell lymphomas (1 paper, 2025). "In contrast, mutations in PIK3CD and CREBBP were associated with inferior outcomes in T-cell lymphomas, highlighting the immunophenotype-specific impact of genetic alterations on treatment responses." (PMID 40506464, 2025).
Thrombocytopenia (1 paper, 2021). A reduction in the number of circulating thrombocytes. "P3 had no signs of infection, but presented with refractory thrombocytopenia and seizures; he possessed a missense variant in the CREBBP gene and was diagnosed with Rubinstein‐Taybi syndrome 1 (OMIM: 180849)." (PMID 33777394, 2021).
tongue squamous cell carcinoma (1 paper, 2023). A squamous cell carcinoma that arises from the tongue. "Our previous research indicated the anticancer effects of Akt, Porcupine, β-catenin, and CREBBP inhibition in tongue squamous cell carcinoma cell lines." (PMID 38132445, 2023).
tumor-predisposition syndromes (1 paper, 2025).
yang deficiency (1 paper, 2022). Yang deficiency is a concept from traditional Chinese medicine. "Using WGCNA and functional analysis, CREBBP is coincidentally identified as a cofactor gene in regulating either Yin or Yang deficiency." (PMID 35341155, 2022). "The mean value of CREBBP-related z-score is 0.541 (Yang deficiency) and −0.541 (Yin deficiency)." (PMID 35341155, 2022). "The symptomatic gene targets for Yang deficiency (KAT2B, NFKB2, CREBBP, GTF2H3) or Yin deficiency (JUNB, JUND, NGLY1, TNF, RAF1, PPP1R15A) were potentially discovered." (PMID 35341155, 2022). "In particular, KAT2B, NFKB2, CREBBP, and GTF2H3 were the key contributive targets for the Yang deficiency group." (PMID 35341155, 2022). "KAT2B, NFKB2, CREBBP, and GTF2H3 are represented as candidate markers for Yang deficiency." (PMID 35341155, 2022).
tumor (213 papers, 2006 to 2025). "Phylogenetic analysis of serial biopsies has identified a CREBBP gene mutation as an early event in the evolution of the tumor genome in FL." (PMID 40725159, 2025). "Missense mutations of the CREBBP gene appear at the early stages of the evolution of the tumor genome." (PMID 40725159, 2025). "Both CREBBP and p300 have HAT activity; hence, p300 inhibitors can induce synthetic lethality for CREBBP-deficient tumor cells by inhibiting compensatory p300 activation in lung and hematopoietic cancer cells through the regulation of MYC promoter activity." (PMID 40599851, 2025). "CREBBP plays a significant role in oncogenesis, with inactivation associated with increased tumor penetrance and dissemination." (PMID 40507954, 2025). "Additional driver alterations are necessary for the appearance of a tumor and 90% of patients with FL have certain mutations in genes regulating transcription and chromatin remodeling such as CREBBP, EP300, KMT2D and EZH2." (PMID 40725159, 2025). "In relapsed/refractory cHL tumor samples, CREBBP was the most frequently mutated gene, being affected in 60.0% of the patients." (PMID 38473705, 2024). "At relapse, emerging subclonal mutations affected key genes associated with SCLC biology, and tumours harbouring clonal CREBBP/EP300 alterations underwent genome duplications." (PMID 38480884, 2024). "The pieces of the Notch puzzle in B-cell lymphoma are slowly appearing in the literature; for example, in DLBCL, Notch signaling mediates M2 polarization of tumor-associated macrophages (TAMs) through the CREBBP/EP300-FBXW7-Notch-CCL2/CSF1 pathway." (PMID 39518937, 2024). "Although CREBBP gene can act as both oncogenes and tumor suppressor genes, they probably functioned as tumor suppressor genes at EBL onset because all observed mutations were inactivating forms, such as stop-gained and frameshift mutations." (PMID 39404261, 2024). "CREBBP/EP300 mutations lead to loss of MHCII expression in tumor cells and subsequently promote the development and progression of hematologic malignancies by facilitating immune escape." (PMID 36831561, 2023). "DLBCL with CREBBP mutations shows depletion of tumor-infiltrating CD4+ T cells, while EP300 mutation is associated with M2 macrophage polarization, which induces an immune-suppressive TME." (PMID 36765793, 2023). "Genes disturbed by CREBBP mutation are direct targets of the BCL6/SMRT/HDAC3 tumor–repressor complex." (PMID 36831561, 2023). "For this purpose, the authors performed a genomic analysis in a cohort of DLBCL patients, in which it was shown that CREBBP/EP300 mutations were associated with tumor progression." (PMID 35326620, 2022). "In conclusion, CLMA performed on tumor biopsies from patients with newly-diagnosed GCB DLBCL/HGBL revealed frequent mutations in CREBBP which were predicted to result in loss of function as well as a significantly lower rate of estimated DFS at 2 years." (PMID 36441737, 2022). "Our analysis demonstrates that the presence of CREBBP mutations in tumor biopsies from patients with newly-diagnosed GCB DLBCL/HGBL is associated with poorer DFS following treatment with front-line immunochemotherapy." (PMID 36441737, 2022). "The present study is the largest to report directly on CREBBP as a gene associated with tumor prognosis." (PMID 36514795, 2022). "Molecular profiling of her tumor demonstrated the following genetic mutations: CREBBP Y1450 C, MLL2 Q1949 * and PIK3R1 Q329." (PMID 35267638, 2022).